ABCC3 (ATP binding cassette subfamily C member 3)
Diseases named in the same sentence as ABCC3 in open-access papers (continued):
Sharing a sentence is not in itself a finding about the gene and the disease.
glioblastoma (16 papers, 2010 to 2025). The most malignant astrocytic tumor (WHO grade IV). "The predictive role of ABCC3 in the survival and prognosis of glioblastoma patients reveals a newfangled translational diagnostic and/or therapeutic relevance of NbA42 and NbA213 in the clinics." (PMID 36585418, 2022). "In another study, overexpression of ABCC3 in glioblastoma multiforme (GBM) was shown to be associated with high risk for death." (PMID 27171227, 2016). "Performing agnostic bioinformatic analysis from glioblastoma patient datasets, we identified ATP Binding Cassette subfamily C member 3 (ABCC3) as a suitable target for immunotargeted applications." (PMID 36585418, 2022). "The expression of ABCC3 increases following TMZ treatment in glioblastoma cell lines, in a concentration and time-dependent manner." (PMID 36585418, 2022). "Circ-ABCC3 expression was significantly increased in stage III glioblastoma tissues compared to stage I + II glioblastoma tissues, strongly linked to the tumor-node-metastasis (TNM) stage." (PMID 35883576, 2022). "We found a similar correlation between CD44, FUT4 (CD15) and ABCC3 expression across glioblastoma patient datasets." (PMID 36585418, 2022). "Detection of ABCC3 by NbA42 and NbA213 was further achieved in two orthotopic glioblastoma mouse models with different degrees of BBB disruption." (PMID 36585418, 2022). "In agreement with other reports we found that ABCC3 is highly expressed in glioblastoma samples, correlates with tumor grade and worse prognosis of patients." (PMID 36585418, 2022). "One hour after systemic administration, both nanobodies recognized ABCC3-expressing heterotopic xenografted glioblastoma tumors." (PMID 36585418, 2022). "Two nanobodies targeting ABCC3 (NbA42 and NbA213) were further characterized and demonstrated in vivo selective recognition of ABCC3 in glioblastoma xenograft mouse models upon systemic administration." (PMID 36585418, 2022). "Circ-ABCC3 deficiency decreased cell proliferation, migration, invasion, tube formation, and PI3K/AKT pathway activation in glioblastoma but promoted cell death." (PMID 35883576, 2022). "Single-chain variable fragments (scFvs) against ABCC3 have been used in preclinical models of glioblastoma." (PMID 36585418, 2022). "Performing agnostic bioinformatic analysis across multiple datasets we identified ABCC3 as a suitable candidate to develop immunotargeted tools for glioblastoma." (PMID 36585418, 2022). "Circ-ABCC3 influenced the growth of glioblastoma via the miR-770-5p/SOX2 axis and the PI3K/AKT pathway." (PMID 35883576, 2022). "NbA42 and NbA213 recognized ABCC3-expressing cells in glioblastoma heterotopic xenografted tumor-bearing mice." (PMID 36585418, 2022). "We identified three immunogenic epitopes of ABCC3 which were used to isolate nanobodies from a glioblastoma-specific phage-display nanobody library." (PMID 36585418, 2022). "Inhibitors of miR-770-5p attenuated the effects of circ-ABCC3 silencing on glioblastoma development, angiogenesis, and the PI3K/AKT pathway." (PMID 35883576, 2022). "Importantly, high expression of ABCC3 is restricted to glioblastoma, with negligible levels in healthy brain tissue, and further correlates with tumor grade and stemness markers." (PMID 36585418, 2022). "NbA42 and NbA213 also target ABCC3-expressing glioblastoma cell lines." (PMID 36585418, 2022). "Then, ABCC3 could represent a new molecular target of glioblastoma which may facilitate the subsequent development of molecular imaging approaches for patient management." (PMID 36585418, 2022). "Also, several reports have elucidated a plausible role of ABCC3 in the pathology and prognosis of glioblastoma patients." (PMID 36585418, 2022). "ABCC3 may constitute a promising target for future molecularly targeted clinical intervention of glioblastoma." (PMID 36585418, 2022). "Importantly, we found a correlation between the expression of stemness markers (CD44 and FUT4 (CD15)) with ABCC3 in glioblastoma." (PMID 36585418, 2022).
glioblastoma (continued). "Future applications of both nanobodies targeting ABCC3 may allow the development of novel glioblastoma theragnostic procedures." (PMID 36585418, 2022). "We also observe high levels of expression of ABCC3 in a panel of glioblastoma cell lines." (PMID 36585418, 2022). "Also, SOX2 mediates transcription of ABCC3 in glioblastoma cells." (PMID 36585418, 2022). "Therefore, we further investigated the role of ABCC3 in glioblastoma." (PMID 36585418, 2022). "Among them, we selected ATP-Binding Cassette subfamily C member 3 (ABCC3, also known as MRP3) as a biomarker of glioblastoma, suitable for further development of immunotargeted applications with clinical impact." (PMID 36585418, 2022). "Circ-ABCC3 and SOX2 expression were significantly increased in glioblastoma tissues and cells; however, miR-770-5p expression was substantially decreased compared to control groups." (PMID 35883576, 2022). "It was also reported that upregulation of miR-9 levels led to the inhibition of ABC transporters, including MDR1, ABCC3, and ABCC6, which reversed MDR in glioblastoma cells." (PMID 35804989, 2022). "It has been demonstrated that miR-381 overexpression effectively sensitized glioblastoma U251 cells to temozolomide by targeting various ABC transporters including ABCG2, ABCC3, and ABCC5." (PMID 35804989, 2022). "Our data demonstrated that either suppressing miR-381 or enforcing NEFL expression inhibited the expression of multidrug resistance factors (ABCG2, ABCC3, and ABCC5) in glioblastoma cells in the presence of TMZ." (PMID 25605243, 2015). "miRNA-381 may target multidrug resistance proteins (ABCG2, ABCC3, ABCC5) and stemness factors, enhancing glioblastoma sensitivity to temozolomide, while reducing the molecular level of miRNA-318 can lead to drug resistance in glioblastoma." (PMID 40675967, 2025). "A possible role for ABCC3 in TMZ resistance and cancer stemness could be hypothesized in glioblastoma." (PMID 36585418, 2022).
pancreatic cancer (14 papers, 2010 to 2025). "ABCC3 plays a key role in drug disposition and has been implicated in cancer cell survival and proliferation, particularly in pancreatic cancer." (PMID 40427480, 2025). "Recent reports demonstrated that disruption of ABCC3 function reduces pancreatic cancer cell growth in vitro and in vivo." (PMID 35008510, 2021). "Although MRP3/ABCC3 transports fewer anticancer substrates than MRP1, overexpression of MRP3 has been predicted to be a prognostic factor in childhood and adult acute lymphoblastic leukemia and adult acute myeloid leukemia and pancreatic carcinoma." (PMID 22837662, 2012). "This approach aimed to identify small-molecule modulators of ABCC3 that may enhance chemosensitivity and contribute to improved therapeutic outcomes in pancreatic cancer." (PMID 40427480, 2025). "In pancreatic cancer, the closely related ABCC3 mediates LPI efflux." (PMID 32718079, 2020). "Other novel FTSEC biomarkers that are overexpressed in HGSOCs include CELSR3, an atypical cadherin; ABCC3, an ABC transport protein implicated in drug resistance; and CTHRC1, a secreted protein shown to be a candidate biomarker for breast and pancreatic cancer." (PMID 24070420, 2013). "The KPC mouse is the most physiologically relevant mouse model of pancreatic cancer, which reproduces the human pathology and progression of pancreatic cancer, therefore providing important pre-clinical validation that it is feasible to inhibit ABCC3 with a small molecule such as MCI-715." (PMID 31378204, 2019). "Previous work investigated that chemoresistance in pancreatic cancer cells was via regulating the expressions of MDR genes including ABCB1, ABCC1, ABCC3 and ABCC5." (PMID 26709920, 2015). "Our results indicate that ABCC3 inhibition with MCI-715 demonstrated strong antitumor activity and is well tolerated, which leads us to conclude that ABCC3 inhibition is a novel and promising therapeutic strategy for a considerable cohort of patients with pancreatic cancer." (PMID 31378204, 2019). "Furthermore, we show that stromal cells in pancreatic tumours, which actively participate in PDAC progression, are enriched for ABCC3, and that its inhibition may contribute to stroma reprogramming." (PMID 31378204, 2019).
colon carcinoma (11 papers, 2009 to 2025). "In rectal cancer compared to colon cancer, ABCC3, RFC‐1, and MTHFD2 expression was significantly lower, while TYMS expression was higher." (PMID 40357991, 2025). "Complementary to this, human colon cancer cell lines may also express other efflux transporters, such as ABCG2 (breast cancer resistance protein, BCRP), ABCC3 (multidrug resistance-associated protein 3, MRP3) and ABCC2 (multidrug resistance-associated protein, MRP2)." (PMID 36983038, 2023). "The present study showed that the expression of ABCC3, MTHFD2, and RFC‐1 was lower, and TYMS higher, in rectal compared to colon cancer." (PMID 40357991, 2025). "These DEGs, significantly altered in human colon cancer tissue (TCGA) (Supplemental S4), are ones with both emerging roles (SEC24D, ABCC3, ATGL2B, and PCK2) and established roles (MYC and MUC2) in colonic tumorigenesis." (PMID 34845203, 2021). "Despite the thorough database search and the data supporting the expression of ABCC3 and ABCG2 in colon cancer cells, no expression of these transporters was detected in our Colo 320 samples." (PMID 36839907, 2023).
hepatocellular carcinoma (9 papers, 2013 to 2022). A malignant tumor that arises from hepatocytes. "This research was implemented in a phase I clinical trial to study the effect of ABCC3-derived peptide in patients with hepatocellular carcinoma." (PMID 32587767, 2020). "ABCC3 was significantly expressed in hepatocellular carcinoma biopsies and non-small cell lung carcinoma." (PMID 27171227, 2016).
osteosarcoma (9 papers, 2011 to 2024). A usually aggressive malignant bone-forming mesenchymal neoplasm, predominantly affecting adolescents and young adults. "The ABCC3 gene rs4793665 polymorphism was significantly associated with methotrexate pharmacokinetics both in juvenile idiopathic arthritis and in pediatric osteosarcoma patients." (PMID 35328066, 2022). "In this study, we planned to investigate the role of three genetic polymorphisms (ABCB1 C3435T, ABCG2 c421A, and ABCC3 C-211T) in response to chemotherapy and overall survival of osteosarcoma patients." (PMID 25097538, 2014). "Cox regression analysis of association between ABCB1 C3435T, ABCG2 C421A and ABCC3 C-211T polymorphisms and the survival of osteosarcoma were showed in Table-IV." (PMID 25097538, 2014). "Further studies are greatly needed to confirm the association between ABCC3 C-211T polymorphism and clinical outcome of osteosarcoma." (PMID 25097538, 2014). "Therefore, we investigated that polymorphisms in ABCB1, ABCG2 and ABCC3 could be a predictor for treatment response for osteosarcoma patients." (PMID 25097538, 2014). "The expression of ABCB1 and ABCC3 in osteosarcoma metastatic tumour biopsies confers impoverished event-free and overall survival outcomes." (PMID 39335211, 2024). "Genetic variants in ABCC3, ABCC5, FasL, GLDC and GSTP1 were repeatedly associated to osteosarcoma treatment outcome, using very heterogeneous efficacy outcomes." (PMID 36536332, 2022). "Since ABCB1 and ABCC3 proteins are relevant for preserving liver integrity at high doses of MTX, these variants are promising biomarkers for MTX-induced hepatotoxicity in localized osteosarcoma patients." (PMID 39771563, 2024). "On the other hand, the ABC transporters (including the ABCC3 and ABCB1 gene products) are transmembrane ATP-dependent efflux pumps that block chemotherapy drugs from entering osteosarcoma tumour cells, leading to poor outcomes and systemic toxicity." (PMID 39335211, 2024). "In our study, the ABCC3 and ABCB1 genes in the osteosarcoma tissues were significantly downregulated compared to the healthy donors." (PMID 39335211, 2024). "As ABC transporters are downstream of Nrf2, the absence of Nrf2 enhanced the sensitivity of osteosarcoma to doxorubicin, cisplatin, and sorafenib and resulted in decreased expression of ABCC3, ABCC4, and ABCG2." (PMID 34473785, 2021).
colorectal cancer (8 papers, 1997 to 2025). A primary or metastatic malignant neoplasm that affects the colon or rectum. "Downregulation of ABCC3 increases drug retention and sensitivity to doxorubicin and 5-fluorouracil in breast and colorectal cancers." (PMID 40839607, 2025). "The expression levels of PGR and ABCC3 were significantly different between the colorectal cancer stages." (PMID 36843944, 2023). "Furthermore, a positive association between 3-year progression-free survival and ABCC3/MRP3 expression was found in patients with advanced colorectal cancer (n = 294)." (PMID 30867007, 2019).
bladder cancer (7 papers, 2011 to 2025). "The upstream interaction between miR-143 and FOXD2-AS1 causes an enhancement of ABCC3 in bladder cancer correlates with previous reports of ABCC3 being elevated in bladder cancer tissue." (PMID 35582574, 2019). "ABCC3 was highly expressed in urinary bladder cancer, and its knockdown inhibited cell growth, drug-resistant ability, and aerobic glycolysis of bladder oncocytes." (PMID 34976054, 2021).
leukemia (6 papers, 2009 to 2023). A malignant (clonal) hematologic disorder, involving hematopoietic stem cells and characterized by the presence of primitive or atypical myeloid or lymphoid cells in the bone marrow and the blood. "Based on the evidence that the expression and the activity of ABCC3 can be modulated by single nucleotide polymorphisms (SNPs), we have investigated and associated to the prognosis, the presence of six different SNPs, previously reported in normal cells, including liver or skin and in leukemia." (PMID 31771235, 2019). "Various cytochromes genes and the ABCC3 were highly upregulated in all primary leukemia cells from different patients under 3D BM niche-like AML disease model culture conditions, which the cells use to metabolize and extrude drugs." (PMID 37932837, 2023). "ABCC3 expression and efflux activity have been described in leukemia cells." (PMID 31771235, 2019).
acute lymphoblastic leukemia (5 papers, 2012 to 2024). Leukemia with an acute onset, characterized by the presence of lymphoblasts in the bone marrow and the peripheral blood. "In particular, the overexpression of MRP1 (ABCC1), MRP2 (ABCC2), MRP3 (ABCC3), MRP5 (ABCC5), and MRP6 (ABCC6) correlates with a poor prognosis in acute lymphoblastic leukemia in both adults and children." (PMID 36978873, 2023). "It has been reported that ABCC1, ABCC2, ABCC3, ABCC4, ABCC5 and ABCC6 play a significant role in MDR mediated non-small cell lung cancer (NSCLC), breast cancer, prostate cancer, colorectal cancer, ovarian cancer and acute lymphoblastic leukemia (ALL)." (PMID 25191874, 2014).
prostate carcinoma (5 papers, 2015 to 2024). A carcinoma that arises from epithelial cells of the prostate gland. "Our results provide evidence for EV-contained ct-SLCO1B3 and ABCC3 as novel, EV-based tumor markers for prostate cancer progression." (PMID 38213719, 2024). "ABCC3 expression has been found to be very low in prostate cancer specimens while ABCC1 is upregulated." (PMID 32718079, 2020). "This study investigated whether ct-SLCO1B3 and ABCC3 can be detected in prostate cancer-derived EVs." (PMID 38213719, 2024). "This demonstrates that ABCC1, but not ABCC3, plays a key role in prostate cancer progression." (PMID 32718079, 2020).
gallstones (4 papers, 2015 to 2025). Solid crystalline precipitates in the biliary tract, usually formed in the gallbladder, resulting in the condition of cholelithiasis. "The aim of this study was to investigate the association between SLCO1B3 (rs4149117:G>T, rs7311358:A>G) and ABCC3 (rs4793665:T>C, rs11568591:G>A) genetic variants and susceptibility to cholesterol gallstone disease, as well as gallstone composition." (PMID 35328066, 2022). "We cannot exclude minor effects of SLCO1B3 and ABCC3 genetic polymorphisms on gallstone disease risk and gallstone composition, which could be masked by the variability of environmental factors within investigated patient populations." (PMID 35328066, 2022). "The components of gallstones were compared between the ABCC3 and SLCO1B3 genotypes." (PMID 35328066, 2022). "The results of this study suggest that polymorphisms of SLCO1B3 and ABCC3 genes are not a valuable marker of gallstone disease susceptibility and do not influence gallstone composition." (PMID 35328066, 2022). "The results suggest that common polymorphisms in SLCO1B3 and ABCC3 genes are not a valuable marker of gallstone disease susceptibility and do not influence gallstone composition." (PMID 35328066, 2022). "However, substantial variability in gallstone composition between individuals observed in the current study was not related to SLCO1B3 nor ABCC3 genotypes." (PMID 35328066, 2022).
neuroblastoma (4 papers, 2001 to 2021). Neuroblastoma (NB) is the most common solid, extracranial childhood tumor. "ABCC1, ABCC3, and ABCC4 have been suggested to be linked with tumor growth and prognosis in neuroblastoma." (PMID 34650973, 2021). "In neuroblastoma, ABCC3 was shown to be very important, albeit as a positive prognostic indicator." (PMID 33081264, 2020). "In patients with childhood neuroblastoma, low (rather than high) ABCC3 expression were predictive of poor survival." (PMID 33531973, 2021).
triple-negative breast carcinoma (4 papers, 2021 to 2023). An invasive breast carcinoma which is negative for expression of estrogen receptor (ER), progesterone receptor (PR), and human epidermal growth factor receptor 2 (HER2). "In triple-negative breast cancer, Cur enhanced doxorubicin sensitivity by miR-181B-2-3p/ABCC3 axis to inhibit tumor growth." (PMID 35942374, 2022). "For instance, ABCC3 was found to be involved in the regulation of the sensitivity of doxorubicin in triple-negative breast cancer." (PMID 34976054, 2021). "In patients with triple-negative breast cancer, the highest mean expression level compared to the normal tissue surrounding the tumor was noted for the ABCC3 gene (M = 0.038216), while the lowest mean expression level was recorded for the ABCC6 gene (M = −0.949418)." (PMID 36674773, 2023).
brain tumor (3 papers, 2010 to 2024). "We next evaluated the potential of NbA42 and NbA213 to detect ABCC3-expressing orthotopic brain tumors." (PMID 36585418, 2022).
Dubin-Johnson syndrome (3 papers, 2019 to 2024). Dubin-Johnson syndrome (DJS) is a benign, inherited liver disorder characterized clinically by chronic, predominantly conjugated, hyperbilirubinemia and histopathologically by black-brown pigment deposition in parenchymal liver cells. "Recent studies demonstrated that patients with Dubin-Johnson syndrome and Abcc2 knockout rats expressed the Abcc3 gene at a higher level in comparison to WT rats." (PMID 30611276, 2019).